MIR6511A1 (microRNA 6511a-1)
Synonyms: hsa-mir-6511a-1; MIR6511A-1
Gene: MicroRNA gene on chromosome 16 (14,925,937 to 14,926,003, forward strand). Ensembl gene ENSG00000275259.
Homologues: Paralogues in human: MIR6511A2 (100% identical), MIR6511A3 (100% identical), MIR6511A4 (100% identical).